RNU6-735P (RNA, U6 small nuclear 735, pseudogene)
Gene: Small nuclear RNA gene on chromosome 12 (95,438,737 to 95,438,843, reverse strand). Ensembl gene ENSG00000222544.
Homologues: Orthologues: chimpanzee U6 (84% identical), macaque U6 (78% identical). Paralogues in human: RNU6-1209P (87% identical), RNU6-1309P (83% identical), RNU6-204P (83% identical), RNU6-560P (83% identical), RNU6-774P (83% identical), RNU6-797P (83% identical), RNU6-11P (82% identical), RNU6-183P (82% identical), RNU6-24P (82% identical), RNU6-37P (82% identical), RNU6-744P (82% identical), RNU6-83P (82% identical), and 1287 more.